MTCL1 (microtubule crosslinking factor 1)
Description:
Microtubule-associated factor involved in the late phase of epithelial polarization and microtubule dynamics regulation. Plays a role in the development and maintenance of non-centrosomal microtubule bundles at the lateral membrane in polarized epithelial cells. Required for faithful chromosome segregation during mitosis.
Synonyms: CCDC165; KIAA0802; SOGA2
Tractability: Antibody: UniProt places it where antibodies can reach, with medium confidence; its Gene Ontology location is reachable by antibodies, with medium confidence. PROTAC: ubiquitination databases record sites on it.
Gene: Protein-coding gene on chromosome 18 (8,705,271 to 8,832,780, forward strand). Ensembl gene ENSG00000168502.
Subcellular location: Lateral cell membrane; Apical cell membrane; Cytoplasm, cytoskeleton, spindle pole; Midbody; Cytoplasm, cytoskeleton
Gene Ontology:
Molecular function: microtubule binding; protein binding; RNA binding; protein homodimerization activity
Biological process: chromosome segregation; establishment or maintenance of epithelial cell apical/basal polarity; microtubule bundle formation; positive regulation of protein targeting to membrane; regulation of autophagy
Cellular component: cytoskeleton; kinetochore; midbody; spindle microtubule; spindle pole; apical plasma membrane; apicolateral plasma membrane; lateral plasma membrane; microtubule bundle
Genetic constraint (gnomAD): Loss-of-function variants: 75 observed, 137.15 expected, observed/expected ratio (o/e) 0.55, 90% interval 0.45 to 0.66. The upper end of that interval is the gene's LOEUF score, 0.66, which puts it in group 2 of 6, group 1 being the genes least tolerant of losing a copy. Missense variants: 2,161 observed, 2,135.4 expected, observed/expected ratio (o/e) 1.01, 90% interval 0.98 to 1.05. Synonymous variants: 910 observed, 888.82 expected, observed/expected ratio (o/e) 1.02, 90% interval 0.97 to 1.08.
Homologues: Orthologues: macaque MTCL1 (97% identical), chimpanzee MTCL1 (94% identical), rat Mtcl1 (83% identical), dog MTCL1 (83% identical), mouse Mtcl1 (80% identical), pig MTCL1 (75% identical), rabbit MTCL1 (71% identical), guinea pig MTCL1 (63% identical), tropical clawed frog mtcl1 (53% identical), zebrafish mtcl1 (15% identical). Paralogues in human: MTCL2 (32% identical), MTCL3 (20% identical).
Diseases named in the same sentence as MTCL1 in open-access papers:
MTCL1 is named in the same sentence as 11 diseases in open-access papers, as found by Europe PMC text mining. Sharing a sentence is not in itself a finding about the gene and the disease. The quoted sentences say what the papers report.
Ataxia (2 papers, 2019 to 2024). Ataxia refers to impaired coordination of voluntary muscle movement. "Furthermore, a point mutation in the C-terminal microtubule-binding domain of MTCL1 has been found to segregate in a Japanese dominant spinocerebellar ataxia family." (PMID 30866998, 2019). "Of note, the deletion also involved MTCL1 which previously has been proposed as a candidate gene for ataxia." (PMID 39359478, 2024).
MTCL1 also shares sentences with these, for which no sentence is quoted: laryngeal squamous cell carcinoma (2 papers); Autoimmunity (1); cancer (1); chronic obstructive pulmonary disease (1); diabetes (1); laryngeal carcinoma (1); lung carcinoma (1); pulmonary fibrosis (1); thyroid disease (1); tumor (1).